ALB (albumin)
Diseases named in the same sentence as ALB in open-access papers (continued):
Sharing a sentence is not in itself a finding about the gene and the disease.
Stroke (continued). "For example, in a clinical study, researchers found that the red cell distribution width-albumin (RA) ratio predicted stroke-related infections and mortality in stroke patients." (PMID 37342335, 2023). "Serum albumin levels with the onset and course of stroke have already been examined in several investigations." (PMID 37682189, 2023). "Intracerebral hemorrhage (ICH) is a severe stroke subtype with a high mortality rate; the lactate-to-albumin ratio (LAR) is a new biomarker for predicting clinical outcomes in patients with ICH." (PMID 37521289, 2023). "When constructing multivariate regression equations, an independent correlation between NIHSS, BMI, and Albumin and the poor outcome of stroke was found (P < 0.05), which was the basis of further exploring the predication value of these indexes." (PMID 36973674, 2023). "While the significance of these findings remains to be understood, evidence in stroke care suggests that raised albumin levels from CKD contribute to endothelial dysfunction and vascular damage and increases the chance of a haemorrhagic stroke." (PMID 37908011, 2023). "By contrast, Bolayir and colleagues (2014) showed in a cohort of 51 patients with acute stroke that the CSF IgG level, the CSF IgG/albumin ratio as well as the CSF IgG index were significantly higher in patients with recurrent stroke." (PMID 37000850, 2023). "In summary, we used several highly interpretive machine learning models to predict stroke prognosis with the highest accuracy to date and to identify heterogeneous treatment effects of warfarin and human albumin in stroke patients." (PMID 36816575, 2023). "Other studies found that serum albumin was closely associated with CVD including heart failure, stroke, and coronary artery disease, and overall survival in CKD patients." (PMID 38156280, 2023). "The 10 variables in order of importance are race, age, PHQ-9 score, HbA1c, sleep duration, BMI, DII, albumin, stroke history, and direct HDL-cholesterol level." (PMID 37179565, 2023). "At 1–7 days post-stroke, we detected time-dependent increase in the ChP blood-CSF barrier permeability to albumin, tight-junction damage, and dynamic changes of SPAK-NKCC1 protein complex, a key ion transport regulatory system for CSF production and clearance." (PMID 38107410, 2023). "We evaluated the impact of pre-stroke glycemic variability measured using glycated albumin (GA) on hematoma expansion and clinical outcomes following spontaneous intracerebral hemorrhage (ICH)." (PMID 37553363, 2023). "We used several highly interpretive machine learning models to predict stroke prognosis with the highest accuracy to date and to identify heterogeneous treatment effects of warfarin and human albumin in stroke patients." (PMID 36816575, 2023). "GNRI, PNI and CONUT score have become very popular and frequently used in the last few years in stroke patients, being, in different ways, based on simple information on weight, albumin, lymphocyte count and total cholesterol." (PMID 37836427, 2023). "Univariate analysis showed that age > 75 years, history of stroke, preoperative albumin ≤ 35 g/L, preoperative Hb ≤ 100 g/L, preoperative PaO2 ≤ 60 mmHg, and time between admission to surgery > 3 days, were risk factors of postoperative delirium." (PMID 37291556, 2023). "Regression analysis showed that stroke severity (RR = 1.76; 95%CI:1.09–2.86) and albumin greater than 3.5 mg/dL (RR = 0.53; 95%CI: 0.36–0.79) were independent risk factors for the presence of in-hospital complications." (PMID 37305511, 2023). "This study found that race, age, PHQ-9 score, HbA1c, sleep duration, BMI, DII, albumin, stroke history, and direct HDL-cholesterol level are considered important determinants of cognitive function in the elderly population of the United States." (PMID 37179565, 2023). "We have previously collected blood samples from stroke patients and analyzed various parameters; a notable finding is low levels of albumin and lymphocytes." (PMID 37760793, 2023).
Stroke (continued). "There were significant differences in stroke history, dementia, BMI, serum albumin level, GNRI, and NRI between the two groups." (PMID 36595498, 2023). "We found that there is a sustained breakdown of the blood-CSF barrier in the mouse ChP at 1–7 days subacute post-stroke stage, which was reflected by CPEC uptake and/or leakage of blood plasma albumin into CSF during the post-stroke subacute period (days 1–7)." (PMID 38107410, 2023). "With a retrospective cohort consisting of 412 cases, one study suggested that clinical and laboratory parameters collected at admission were correlated with UTI after stroke, including older age, higher serum urea, and higher serum albumin." (PMID 37780719, 2023). "A study from China using a nomogram chart prediction model found that ALB was one of the predictors of death within 6 months of stroke onset (OR = 0.854, 95% CI = 0.774 − 0.931, P < 0.01)." (PMID 36567762, 2022). "Weight, BMI, TP, TG, HGB, and serum albumin reflect the body nutrition state, and if patients with stroke had sufficient levels of nutrition state, they would have more energy to resist the enhanced catabolism caused by inactivity and immobilization." (PMID 36003303, 2022). "Levels of urinary microalbumin and urinary albumin-to-creatinine ratio showed approximately linear associations with risk of CHD and stroke, which were somewhat attenuated after adjustment for traditional risk factors." (PMID 36314129, 2022). "Previous studies suggested that a low serum albumin concentration was an independent predictor of incident cardioembolic and cryptogenic stroke among 2,986 patients free of stroke for 12 years." (PMID 36186979, 2022). "Age, rurality and stroke were predictors of poor outcomes, while admission for arrhythmia, ACE inhibitor/angiotensin II receptor blocker use, high albumin and digoxin use were associated with better outcomes." (PMID 35641098, 2022). "criteria ALB, hsCRP, and Hcy as independent risk factors for prognosis in patients with PFO-related stroke." (PMID 35756923, 2022). "Low albumin levels significantly enhanced the probability of recurrence in stroke patients and were related with poor outcome in all stroke subtypes." (PMID 36562034, 2022). "A poor education, physical inactivity, stroke, low serum albumin, CKD stage 3–4, macroalbuminuria, and a poor QOL were independent risk factors for depression in the DKD patients." (PMID 36612797, 2022). "In this research, the glycemic variability was defined by glycated albumin (≥16.0%), which showed glycemic fluctuation prior to 4 weeks of stroke onset." (PMID 35711907, 2022). "We observed that low education levels, physical inactivity, stroke, low serum albumin levels, CKD Stages 3–4, macroalbuminuria, and a poor QOL were independently associated with depression among DKD patients." (PMID 36612797, 2022). "Serum albumin level at admission is significantly negatively correlated with infectious complications of stroke patients." (PMID 35849734, 2022). "Our preliminary data suggested that serum albumin-corrected calcium on admission is a potential prognostic biomarker in stroke patients after mechanical thrombectomy." (PMID 36056314, 2022). "In this study, CRP and CAR were more important than CRPc and albumin in predicting mortality of neurocritically ill patients with stroke." (PMID 36079002, 2022). "Subsequently, a large number of observational studies strongly support the correlation between serum ALB and stroke prognosis." (PMID 35756923, 2022). "Although the present study provides valuable insights, prospective large-scale studies are needed to further confirm the usefulness of CRP, CAR, and albumin in predicting clinical outcomes of stroke patients with evidence-based conclusions." (PMID 36079002, 2022). "This is the first study to investigate the relationships between albumin-corrected calcium levels and clinical characteristics and functional outcome in stroke patients after mechanical thrombectomy." (PMID 36056314, 2022).
Stroke (continued). "Existing epidemiological evidence has suggested that reduced blood albumin levels were related to myocardial infarction (MI), atrial fibrillation (AF), heart failure (HF) and stroke." (PMID 35850629, 2022). "In the univariate analysis, we obtained that liver function indicators, including AST, TP, and ALB, were statistically different (p = 0.036, p = 0.003, and p < 0.001, respectively) in stroke prognosis." (PMID 36061892, 2022). "In contrast, stroke brains showed altered albumin distribution in the IL LVCP, reflected with loss of vasculature albumin (leak out from ChP), and/or increased albumin uptake in the CPECs (p < 0.01)." (PMID 35413993, 2022). "With the establishment of the green channel, uric acid and albumin to globulin ratio can be obtained before intravenous thrombolysis in most stroke centers in our country." (PMID 36158944, 2022). "There is some evidence that decreased serum ALB levels possibly were involved in poor functional outcomes within 24 h of stroke." (PMID 36061892, 2022). "Poor education, physical inactivity, stroke, low concentration of serum albumin, CKD stage 3–4, macroalbuminuria, and a poor QOL were independent risk factors for depression in DKD patients." (PMID 36612797, 2022). "We aimed to explore the association between the baseline hypersensitive C‐reactive protein‐albumin ratio (CAR) and stroke‐associated pneumonia (SAP) during hospitalization and the short‐term prognosis in patients with acute ischemic stroke (AIS)." (PMID 35748095, 2022). "Multiple Cox logistic regression hazard analysis revealed that age, cerebrovascular accident, eGFR, urine albumin-to-creatinine ratio, use of painkillers, depressive mood, MUNW and MUOW were independent predictors of RKFD." (PMID 35719641, 2022). "The ALIAS trials (pilot, I and II) used a 2-h infusion of 25% human albumin (within 5 h (part I) or within 16 h (part II) of stroke onset)." (PMID 34666786, 2021). "Low levels of serum albumin have been studied as a prognostic factor for clinical outcomes and mortality not only in patients with stroke but in various other diseases as well." (PMID 33959442, 2021). "Growing research evidence showed that albumin was a useful, independent prognostic factor in patients after stroke." (PMID 35095715, 2021). "Only two-thirds of men 65–74 years of age with serum albumin levels ≥4.4 g/dl have developed strokes compared to patients with albumin levels ≤4.2 g/dl." (PMID 34765635, 2021). "Higher age was significantly associated with higher CCI, presence of cardiovascular diseases and stroke, and lower serum albumin." (PMID 34943514, 2021). "We aimed to elucidate the combined impact of BMI and dysglycemia expressed by glycated albumin (GA) on efficacy of clopidogrel-aspirin therapy among minor stroke (MS) or transient ischemic attack (TIA) patients." (PMID 32544082, 2020). "Second, fluid therapy was started 3 h after the ischemic injury; thus, the role of albumin and saline administration at different time points (particularly later in the course of stroke) has yet to be clarified." (PMID 33013661, 2020). "First, the liver function test results demonstrated that the albumin, albumin/globulin and total protein concentrations in stroke patients was lower than in healthy individuals (P < 0.01), while the globulin concentration was higher (P > 0.05)." (PMID 32071823, 2020). "Serum albumin level, C-reactive protein (CRP), stroke, and age ≥ 70 years were significantly associated with pneumonia defined by CT after adjustment for age." (PMID 33260480, 2020). "At 7 d post stroke, albumin expression remained elevated in the ischemic areas compared to the contralateral non-ischemic MCA areas after p-MCAO, but not 90-min t-MCAO." (PMID 32492968, 2020). "Further, serum albumin and hemoglobin concentrations have a predictive value for stroke recurrence and combined events." (PMID 33510706, 2020).
Stroke (continued). "The multivariable model included variables such as sex, age, albumin, urea, stroke, and MMS examination score." (PMID 32907534, 2020). "In our study, we found that low albumin and N2AC score were associated with a higher incidence of stroke." (PMID 33094925, 2020). "We then applied Cox proportional hazard models to estimate the hazard ratios (HRs) for the association between albuminuria (measured as albumin-to-creatinine-ratio, ACR) and diagnosis of stroke and stroke subtypes." (PMID 32359353, 2020). "The univariate regression analysis showed that an age ≥70 years, a history of stroke, elevated C-reactive protein, and a low albumin level were significantly related to the presence of PLLCT." (PMID 33260480, 2020). "In this regard, the present randomized controlled clinical trial was conducted to examine the effects of ALA supplementation on serum albumin, and inflammatory and oxidative stress markers in stroke patients." (PMID 32373498, 2020). "To investigate changes in permeability of the alveolar-capillary barrier in the model of aspiration-induced post-stroke pneumonia, we measured albumin concentrations in BAL and plasma one day after infection." (PMID 32481512, 2020). "After adjusting potential confounders (age, blood platelet, albumin, stroke severity, triglycerides and low-density lipoprotein [LDL]), multivariate logistic regression analyses indicated that BUN/Cr is independently associated with HT." (PMID 30987606, 2019). "Silver staining of SDS-PAGE gels revealed a significant amount of protein (particularly albumin) in urinary fractions from stroke-induced rats compared with sham-operated rats." (PMID 31784544, 2019). "In this study, we detected a nonlinear relationship between BUN/Cr and HT after adjusting the age, blood platelet, albumin, stroke severity, triglycerides and LDL." (PMID 30987606, 2019). "Similar to its effect in stroke models, deficiency of caveolin-1 significantly mitigated the course of EAE and reduced the albumin uptake by endothelial cells." (PMID 30523362, 2019). "In this process, extravasation of albumin promotes stroke-related complications like epileptic seizures and the vasogenic edema, which detrimentally impacts on the clinical outcome." (PMID 30744693, 2019). "In this study we have identified that increased BBB permeability was sustained to 24 h post-stroke in vehicle-treated animals, as identified by the increased albumin extravasation." (PMID 31333402, 2019). "For 30-day to 5-year mortality, aging, stroke history and AKI Stage 3 were independent risk factors, while albumin level, β-blocker therapy and PCI were independent protective factors." (PMID 29299948, 2018). "The aim of this work is to assess the role of hemorheological parameters (such as blood viscosity, hematocrit, platelet aggregation, and leukocyte count), protein C, protein S, antithrombin III, and serum albumin as predictors of stroke outcome." (PMID 30046235, 2018). "Serum albumin, hematocrit level, and total leukocyte count at the time of presentation of ischemic stroke are useful markers for stroke outcome." (PMID 30046235, 2018). "During the pathological progression of stroke, for example, the compromised blood-brain barrier allows Evans blue-albumin complexes to enter the brain." (PMID 30469316, 2018). "Platelet aggregation was significantly higher and serum albumin was significantly lower in stroke patients compared to control (p value = 0.000 and 0.039) respectively." (PMID 30046235, 2018). "Reduced serum albumin concentrations is associated with increased mortality from CVD, stroke and chronic heart disease." (PMID 30540842, 2018). "In many pathologies of the CNS such as TBI and stroke the brain-blood barrier (BBB) is disturbed which results in extravasation of blood-derived proteins including albumin and inflammatory mediators into the brain tissue." (PMID 28210211, 2017).
Stroke (continued). "In an attempt to mimic these occurrences in the mouse we first characterised the degree of BBB disruption (extravasation of albumin and haemoglobin into the brain) and functional deficit in response to rt-PA under sham conditions and in our MCAo stroke model." (PMID 29157263, 2017). "Previous studies have already shown the safety and efficiency of the high-dose human albumin (0.34–2.05 g/kg) therapy administrated after intravenous rt-PA within 16 hours of stroke onset." (PMID 28798356, 2017). "Second, no information about premorbid renal status was available in our cohort, and urine albumin was only once measured after stroke." (PMID 27213281, 2016). "Since EP1 knockout increased baseline IgG levels in plasma, we utilized albumin levels in the brain as an additional marker of BBB permeability after stroke." (PMID 26648273, 2015). "In our analysis, medical history of stroke, serum albumin levels, dental prosthetic status, plaque score, and periodontal status were related to both age and reduction in salivary flow rate." (PMID 25705657, 2015). "Our previous publication using high-resolution LC-MS/MS to profile protein expression patterns in plasma demonstrated a collection of differently abundant proteins, including albumin and ApoA1, before and 12 months after stroke related PFO closure." (PMID 25678897, 2015). "ALB is known to be neuroprotective in preclinical animal models of stroke and was under clinical trial as a potential neuroprotective agent." (PMID 24752076, 2014). "Compared to NHANESIII, HDL-cholesterol, albumin, and hemoglobin generally were lower (Ps < 0.05) and lipids were more favorable in stroke (Ps < 0.01)." (PMID 25530905, 2014). "Across races and genders, hemoglobin and albumin concentrations were ~5–10% lower in stroke compared to NHANES (Ps < 0.05)." (PMID 25530905, 2014). "Correlation between RDW and albumin, atrial fibrillation, stroke history, and iron and beta-blocker usage was significant but marginal." (PMID 23444243, 2013). "Exogenous administration (continuous infusion) of DHA bound to human albumin has been previously shown to be neuroprotective in an adult rodent stroke model." (PMID 23437099, 2013). "Factors that were noted to have influenced outcome were, patients age at time of stroke, admission stroke severity, serum albumin and total white cell count." (PMID 23565300, 2013). "This study was prompted by our earlier findings demonstrating that omega-3 essential fatty acids (found in fish oil) and human serum albumin (Alb) are beneficial in ameliorating cerebral ischemic injury in rodent stroke models." (PMID 24194876, 2013). "Low admission serum albumin and admission stroke severity measured by NIHSS were an independent determinant of poor outcome." (PMID 23565300, 2013). "We evaluated the impact of baseline albuminuria [urine albumin-creatinine ratio (UACR)≥30 mg/g] or low estimated glomerular filtration rate (eGFR<60 ml/min per 1.73 m2) on stroke patients admitted to the intensive care unit (ICU)." (PMID 24058451, 2013). "Correlation between RDW and serum albumin, atrial fibrillation, stroke history, serum iron, and beta-blocker usage was significant but marginal (r = -0.282, P = 0.038; r = 0.208, P = 0.038; r = 0.227, P = 0.023, r = -0.240, P = 0.016, respectively)." (PMID 23444243, 2013). "In the Tromso Study a high urinary albumin-creatinine ratio (ACR) was associated with an increased risk of myocardial infarction, stroke, and all-cause mortality after a mean follow-up about 10 years." (PMID 23007013, 2012). "Experimental studies showed that high-dose or moderate-dose of human albumin therapy, after stroke onset, is highly effective in improving neurological status and in reducing infarction volume and extent of brain swelling." (PMID 23110752, 2012). "Lately, special attention has been paid to human serum albumin (Alb) therapy, which has been reported to ameliorate neuronal damage during the acute phase of stroke." (PMID 22980673, 2012).